CLEC11A (C-type lectin domain containing 11A)
Diseases named in the same sentence as CLEC11A in open-access papers (continued):
Sharing a sentence is not in itself a finding about the gene and the disease.
cancer (continued). "To further explore CLEC11A expression in human cancers, we examined CLEC11A expression in TCGA." (PMID 33747924, 2021). "The expression profiles of BDP1, CLEC11A, and ID3 genes in cancer cells were detected using qRT-PCR technology." (PMID 40607387, 2025). "Our analysis revealed that, among the genes studied, CLEC11A, ICAM4, ITGA4, and AVP exhibited the highest specificity to AML when compared to other cancer types." (PMID 39484036, 2024). "Furthermore, to understand the biofunction of CLEC11A, we employed functional enrichment analysis and uncovered that the biological processes of CLEC11A co-expression genes were mainly concentrated in the extracellular matrix organization and primarily involved in the cancer signaling pathway." (PMID 38348052, 2024). "Our findings suggested that CLEC11A produced from LAC may promote tumor vascularization and cancer progression." (PMID 35267664, 2022).
tumor (12 papers, 2011 to 2025). "As a member of the C-type lectin superfamily, CLEC11A levels are elevated in the SCGF-α form within imatinib-responsive tumor areas, suggesting a possible role in the imatinib-induced inflammatory response observed in gastrointestinal tract patients." (PMID 37597212, 2024). "Namely, they showed that CLEC11A-expressing cells promoted tumor formation in mice, with markers for angiogenesis, which we would assume would lead to poor survival." (PMID 38466706, 2024). "In terms of tumor grade, there was a progressive increase in CLEC11A expression with each advancing grade." (PMID 37597212, 2024). "We found that CLEC11A expression was significantly elevated in GC when compared to adjacent non-tumor tissues." (PMID 37597212, 2024). "Using shRNA to suppress the expression of CLEC11A led to significant inhibitions of cell cycle progression, migration, and invasion, as well as a marked reduction of in vivo tumor growth." (PMID 38348052, 2024). "Herein, we used bulk tumor RNA-seq information to explore the expression, prognosis value, and genomic alterations of CLEC11A, as well as its immune infiltration in GC." (PMID 38348052, 2024). "The relationships between CLEC11A and prognoses, genetic alterations, tumor microenvironment (TME), and therapeutic responses in GC patients were analyzed by bioinformatics methods." (PMID 38348052, 2024). "Another possibility was that the presence of CLEC11A induced the migration of endothelial cells toward tumor tissues." (PMID 35267664, 2022). "We found that the addition of exogenous CLEC11A in the LL/2 transplantation was sufficient to promote tumor growth and to increase the number of endothelial cells in tumors." (PMID 35267664, 2022). "First, we tested the tumorigenic ability of H1299-CLEC11A in nude mice and found that CLEC11A expression significantly promoted the tumor formation by H1299 cells." (PMID 35267664, 2022). "Additionally, CLEC11A is upregulated in its plasma SCGF-beta (SCGF-β) form within the conditioned medium sourced from human peri-tumor tissue-derived fibroblasts." (PMID 37597212, 2024). "In sum, these findings suggest that CLEC11A might promote GC development and progression through its involvement in inflammatory responses and the tumor immune response." (PMID 37597212, 2024). "Besides investigating the biological functions of CLEC11A in vitro, we also evaluated its in vivo role using a tumor transplantation model." (PMID 38348052, 2024). "This implies that CLEC11A might promote the GC development by participating in tumor immunity, especially by affecting the abundance of infiltrating immune cells, most notably M2 macrophages." (PMID 37597212, 2024). "Our results from cellular and animal studies supported that CLEC11A might promote LAC progression through enhancing tumor angiogenesis." (PMID 35267664, 2022). "Collectively, these data suggested that CLEC11A might promote tumor growth through enhancing angiogenesis." (PMID 35267664, 2022). "CLEC11A could be a novel factor involved in tumor angiogenesis." (PMID 35267664, 2022). "Our findings revealed that HCAFs enhance CRC lymphatic metastasis by secreting CLEC11A, a protein that binds to the LGR5 receptor on tumor cells, subsequently activating the WNT/β-catenin signaling pathway." (PMID 41090363, 2025). "Unsurprisingly, heightened expression of CLEC11A correlated with elevated Dysfunction and Exclusion scores in the TIDE algorithm, signifying increased immune system exclusion by the tumor and a diminished response to immunotherapy." (PMID 38348052, 2024). "The results revealed low expression of ALPL, RUNX2, and CLEC11A in PC, while highly expressed in PT and MLN (all p < 0.05, Wilcoxon test), which suggested abnormal activation and malignant transformation of OB cells during tumor progression." (PMID 38755647, 2024).
tumor (continued). "Moreover, elevated CLEC11A was found to reduce the benefit of immunotherapy according to immunophenoscore (IPS) and the tumor immune dysfunction, exclusion (TIDE)." (PMID 38348052, 2024). "It is possible that CLEC11A secreted from LAC cells facilitated the differentiation of circulating progenitor cells into endothelial cells and the formation of new vessels through vasculogenesis, in the presence of tumor-secreted VEGFs." (PMID 35267664, 2022). "The direct interaction between Cyt c and CETP, CLEC11A, CYP2A6 and CYP2A7 has not been clearly revealed, but they have potential indirect associations in cholesterol metabolism, mitochondrial function, oxidative stress regulation and tumor microenvironment regulation." (PMID 40860340, 2025). "To examine whether the presence of exogenous CLEC11A is sufficient in promoting tumor growth and angiogenesis, we transplanted Lewis lung cancer cells, LL/2, into syngeneic C57BL/6 mice in the presence or absence of CLEC11A addition to the Matrigel matrix." (PMID 35267664, 2022).
immune disorders (1 paper, 2024). "CLEC11A is involved in bone-development regulation, while CLEC16A is associated with various immune disorders, playing a crucial role in immune development." (PMID 39199873, 2024).
neurological diseases (1 paper, 2025). "Recent research has also indicated that CLEC11A participates in the development of several neurological diseases." (PMID 40294019, 2025).
skeletal diseases (1 paper, 2024). "The direct interrelationship between the two should be investigated in the future to provide emerging drug targets for the treatment of skeletal diseases while developing a deeper understanding of the exact mechanisms underlying the action of Clec11a." (PMID 39188913, 2024). "The specific reasons for this phenomenon need to be further explored to provide a direction for the future use of Clec11a in the treatment of skeletal diseases in different age classes." (PMID 39188913, 2024).
skeletal system diseases (1 paper, 2024). "In summary, Clec11a may be closely associated with the skeletal system and has great potential for the treatment of skeletal system diseases." (PMID 39188913, 2024). "The upstream–downstream relationship among Wnt signaling, Clec11a, and its receptor integrin α11 should be further explored to identify additional roles of Clec11a in skeletal system diseases." (PMID 39188913, 2024).
CLEC11A also shares sentences with these, for which no sentence is quoted: lymphoblastic leukemia (3 papers); colorectal cancer (2); COVID-19 (2); depression (2); gastrointestinal tumors (2); acne (1); Anxiety (1); asthma (1); bone tumors (1); breast invasive carcinoma (1); colon adenocarcinoma (1); degenerative disk disease (1); head and neck cancer (1); head and neck squamous cell carcinoma (1); hematologic disorder (1); Hepatitis (1); insomnia (1); lymphoma (1); malaria (1); melancholia (1); Osteopenia (1); pancreatic cancers (1); periodontitis (1); prostate adenocarcinoma (1); Pseudoarthrosis (1); sarcoma (1); spinal stenosis (1); steatosis (1); testicular germ cell tumor (1); Xanthelasma (1).